C9orf72 (C9orf72-SMCR8 complex subunit)
Diseases named in the same sentence as C9orf72 in open-access papers (continued):
Sharing a sentence is not in itself a finding about the gene and the disease.
Splenomegaly (12 papers, 2016 to 2023). Abnormal increased size of the spleen. "Our work differs by showing that the activation of the GRP78-IRE1-XBP1 axis is one of the causes of splenomegaly and inflammation in C9orf72-/- rats." (PMID 36438488, 2022). "While occasional mild splenomegaly was observed in the 2 month old C9orf72 deficient mice, this phenotype becomes more severe with age, with the 4-5 month old C9orf72 deficient mouse having a spleen 2-3 times the size of its littermate control." (PMID 27193190, 2016). "Moreover, the loss of C9orf72 results in primary ER stress with activated UPR in rat spleens, which is one of the causes of splenomegaly with inflammation in C9orf72-/- rats." (PMID 36438488, 2022). "Furthermore, mice harboring loss-of-function mutations in the ortholog of C9ORF72 develop splenomegaly, neutrophilia, thrombocytopenia, increased expression of inflammatory cytokines, and severe autoimmunity, ultimately leading to a high mortality rate." (PMID 36291345, 2022). "Remarkably, splenomegaly and lymphadenopathy in C9orf72−/− mice were greatly reduced after 2 weeks of ruxolitinib treatment and significantly rescued after 3 weeks of ruxolitinib treatment." (PMID 37250330, 2023). "While the physiological functions of C9ORF72 remain to be fully elucidated, the most striking phenotype of C9orf72 knockout mice is enhanced inflammatory responses, resulting in age-dependent lymphadenopathy and splenomegaly." (PMID 37250330, 2023). "C9ORF72 ablation results in lymphadenopathy, splenomegaly, and increased levels of proinflammatory cytokines in mice, supporting the critical role of C9ORF72 in inflammatory responses." (PMID 37250330, 2023). "In post-mortem examination, consistent with recent reports of immune dysregulation in C9orf72 knockout mice, we observed splenomegaly in the C9orf72-/- mice." (PMID 27875531, 2016). "However, the C9orf72-null rats developed other distinct symptoms, such as visible splenomegaly and cervical lymphadenopathy." (PMID 36438488, 2022). "As the C9orf72-null rats exhibited splenomegaly and cervical lymphadenopathy, which is commonly associated with diseases such as chronic lymphocytic leukemia 43, we investigated the expression of immune receptor and inflammatory cytokine genes using RNA-seq, RT-PCR and RT-qPCR assays." (PMID 36438488, 2022). "However, recent studies have observed highest levels of C9ORF72 expression in microglia and C9ORF72 knock out leads to an altered auto‐immune response with age related neuroinflammation leading to progressive splenomegaly and lymphadenopathy in mice." (PMID 28585384, 2017). "The number or GFAP positive cells and Iba-1 positive cells were similar to controls and there was no sign of peripheral inflammation like splenomegaly, previously observed in C9orf72 knockout animals." (PMID 37138765, 2023).
Friedreich ataxia (11 papers, 2017 to 2026). An inherited condition that affects the nervous system and causes movement problems. "AGO:RNA complexes complementary to the disease-associated repeat RNAs of Friedreich’s Ataxia, Fuchs Dystrophy, and C9orf72-related ALS can block R-loop formation or protein association." (PMID 40867050, 2025). "Disease-relevant studies further demonstrate frataxin upregulation in Friedreich's ataxia and reduction of mitochondrial reactive oxygen species in C9orf72-related models." (PMID 41769702, 2026).
progressive supranuclear palsy (11 papers, 2019 to 2025). A rare late-onset neurodegenerative disease characterized by supranuclear gaze palsy, postural instability, progressive rigidity, and mild dementia. "C9orf72 has been linked to typical PD, DLB, Richardson’s syndrome, and CBS." (PMID 40722695, 2025). "Despite MD being frequent in C9orf72 HRE carriers, the phenotypic manifestations do not fall neatly into other syndromic categories, e.g., progressive supranuclear palsy and multiple system atrophy." (PMID 33977144, 2021).
fragile X-associated tremor/ataxia syndrome (10 papers, 2012 to 2022). Fragile X-associated tremor/ataxia syndrome (FXTAS) is a rare neurodegenerative disorder characterized by adult-onset progressive intention tremor and gait ataxia. "Here, we utilized HCR to detect RNA foci associated with G4C2 repeat expansions in C9orf72 that are the most common genetic cause of ALS and FTD and CGG repeats associated with Fragile X disorders such as Fragile X-associated tremor/ataxia syndrome (FXTAS)." (PMID 33892814, 2021). "C9orf72 mRNA with an enlarged 5’-UTR that includes the G4C2 repeats, is similar to FMR1 transcripts associated with fragile X-associated tremor ataxia syndrome (FXTAS), caused by moderate (<200) CGG repeat expansions in the 5’-UTR of the FMR1 gene." (PMID 26916632, 2016).
motor neuron degeneration (10 papers, 2012 to 2026). "Although reduced levels of C9ORF72 protein cause motor neuron degeneration in Caenorhabditis elegans and zebrafish, loss of C9ORF72 in mice did not elicit the ALS or FTD phenotype." (PMID 33679328, 2021). "Early work in zebra danio and worms showed that reduced protein levels of the C9orf72 orthologs lead to motor neuron degeneration, indicating a possible role of C9orf72 loss-of-function in disease phenotype." (PMID 34297726, 2021). "Furthermore, in mouse models, C9‐KO or C9‐HRE and the presence of RNA foci and DPRs have been shown to be insufficient to cause motor neuron degeneration, although loss of C9ORF72 can lead to synaptic dysfunction and excitotoxicity." (PMID 40952044, 2026). "However, partial decrease of C9orf72 levels, or of autophagy processing, leads to widespread accumulation of poly(GP) associated with motor neuron degeneration." (PMID 39316747, 2024). "Studies have shown that C9orf72 regulates energy homeostasis by stabilizing mitochondrial complex I. C9orf72 haploinsufficiency destabilizes mitochondrial complex I and drives motor neuron degeneration." (PMID 35805131, 2022). "We further examined the length of the spinal motor neuron axons in GA80-GFPa zebrafish, since C9orf72 repeat expansion carriers can suffer from motor neuron degeneration." (PMID 28088213, 2017).
tauopathy (8 papers, 2018 to 2025). Neurodegenerative disorders involving deposition of abnormal tau protein isoforms (tau proteins) in neurons and glial cells in the brain. "The three major genes implicated in genetic FTLD are microtubule-associated protein tau (MAPT), progranulin (GRN) and chromosome 9 open reading frame 72 (C9orf72), where MAPT mutations are associated with a primary tauopathy and GRN and C9orf72 are associated with TDP-43 pathology." (PMID 38147792, 2024). "While this study suggests that repeat expansions in C9orf72 are not a genetic risk factor for PSP, CBS, or APS, there is evidence to suggest a genetic basis in familial forms of these conditions, particularly tauopathies." (PMID 40138021, 2025). "We therefore infer that at 53 years old, with the C9orf72 expansion, and a classical FTD presentation, the present case has TDP‐43 pathology without tauopathy." (PMID 30349864, 2018).
Cerebellar atrophy (7 papers, 2018 to 2025). Cerebellar atrophy is defined as a cerebellum with initially normal structures, in a posterior fossa with normal size, which displays enlarged fissures (interfolial spaces) in comparison to the foliae secondary to loss of tissue. "The cerebellum was also affected in mutant mice, and it has been shown that cerebellar atrophy occurs in both mutant C9orf72 and MAPT associated FTD." (PMID 34136812, 2021). "In the current study, we therefore aimed to elucidate the regional brain atrophy focusing on thalamic and cerebellar atrophy in C9orf72 mutation carriers compared to patients with sporadic FTD or FTD/ALS and healthy controls." (PMID 29599716, 2018). "Cerebellar atrophy can be captured in presymptomatic C9orf72 mutation carriers." (PMID 40131525, 2025). "Interestingly, regional cerebellar atrophy was detected in asymptomatic C9orf72 mutation carriers." (PMID 33983551, 2021). "Cerebellar atrophy has been described in those carrying the C9orf72 gene mutation, but not in those carrying the MAPT mutation." (PMID 33983551, 2021).
myotonic dystrophy type 2 (7 papers, 2020 to 2024). Myotonic dystrophy type 2 (MD2), also known as proximal myotonic myopathy, is a very rare genetic multi-system disorder of late childhood or adult-onset characterized by mild myotonia, muscle weakness, and rarely cardiac conduction disorders. "In addition, no foci were detected in C9orf72 mutant astrocytes when using a probe against the myotonic dystrophy type 2 (DM2) repeat expansion (CCTG)n, confirming the specificity of the G4C2 anti‐sense probe." (PMID 31841614, 2020).
primary progressive aphasia (7 papers, 2016 to 2025). Primary progressive aphasia (PPA) is a neurodegenerative disorder, characterized by a primary dissolution of language, with relative sparing of other mental faculties for at least the first 2 years of illness. "The high frequency of primary progressive aphasia (PPA) in our TIA1 mutation carriers is different from those with the C9orf72 mutation whose FTD phenotype is more often bvFTD." (PMID 29216908, 2017). "One study reported the co-occurrence of CHCHD10 and C9orf72 variants in an ALS-FTD patient, and another reported a person carrying both TBK1 and SQSTM1 variants, who was diagnosed with non-fluent variant primary progressive aphasia (nfv-PPA)." (PMID 40170896, 2025).
corticobasal syndrome (6 papers, 2015 to 2025). Corticobasal syndrome (CBS) is a rare neurodegenerative disease characterized by multifaceted motor system dysfunctions and cognitive defects such as asymmetric rigidity, bradykinesia, limb apraxia, and visuospatial dysfunction. "Screening the C9orf72 gene in 37 patients with features of corticobasal syndrome (CBS) detected an expansion in 3 patients, confirmed by Southern blotting." (PMID 25308964, 2015).
Lymphadenopathy (6 papers, 2016 to 2023). Enlargement (swelling) of a lymph node. "Smcr 8-/- mice have similar inflammatory phenotypes as C9orf72-/- mice consisting of splenomegaly, lymphadenopathy, activated circulating T cells and excessive inflammatory cytokine production." (PMID 35303907, 2022). "Progressive splenomegaly and lymphadenopathy, increased levels of pro-inflammatory cytokines, autoinflammation with the production of autoantibodies, and auto-immune like diseases have all been reported in both C9orf72 + / − and C9orf72 − / − knockout mouse models." (PMID 35303907, 2022).
multiple system atrophy (6 papers, 2012 to 2022). Multiple system atrophy (MSA) is a neurodegenerative disorder characterized by autonomic failure (cardiovascular and/or urinary), parkinsonism, cerebellar impairment and corticospinal signs with a median survival of 6-9 years. "To date, as far as we are aware, there have been no reported pathologically confirmed cases of ALS with C9orf72 mutation and multiple system atrophy (MSA)." (PMID 35746899, 2022).
sarcoma (6 papers, 2018 to 2025). A usually aggressive malignant neoplasm of the soft tissue or bone. "The most common genes involved are Chromosome 9 open reading frame 72 (C9orf72), SOD1, TDP-43, fused in sarcoma and TANK-binding kinase 1, which together cause 15% of the ALS cases." (PMID 36751500, 2022). "Despite the growing number and variety of these genes, four of them stand out as the most commonly mutated in ALS: superoxide dismutase 1 (SOD1), chromosome 9 open reading frame 72 (C9orf72), fused in sarcoma/translocated in liposarcoma (FUS/TLS), and TAR DNA-binding protein 43 (TARDBP-43)." (PMID 40422183, 2025). "However, the number of studies involving these animal models, including those carrying the transactive response DNA binding protein of 43 kDa (TDP-43), fused in sarcoma (FUS) and C9orf72, are currently too limited to allow a reliable quantitative population study." (PMID 36613659, 2022).
semantic dementia (6 papers, 2015 to 2023). "Pain and temperature symptoms were commonly described across FTLD syndromes, exhibited by the majority of patients with behavioural variant FTD and semantic dementia and most frequently in the molecular subtype represented by C9orf72 mutations." (PMID 26463677, 2015).
sporadic amyotrophic lateral sclerosis (6 papers, 2021 to 2023). Sporadic amyotrophic lateral sclerosis is a amyotrophic lateral sclerosis in which there is no known cause, such as no family history. "In relation to the comparator groups SOD1 (n = 20) and sporadic amyotrophic lateral sclerosis (n = 753), C9orf72 patients generally obtained the worst results in all domains with the exception of spatial perception which was normal in all three groups." (PMID 37006326, 2023).
cortical atrophy (5 papers, 2018 to 2025). "Our analysis revealed distinct sets of PLS1 genes positively or negatively associated with cortical atrophy for C9orf72-bvFTD, GRN-bvFTD, and MAPT-bvFTD, potentially reflecting molecular mechanisms underlying neuroanatomical changes." (PMID 39920674, 2025). "In contrast to sporadic patients, however, c9orf72 mutation carriers appear to have more parietal and occipital cortical atrophy creating a more diffuse cortical atrophy pattern." (PMID 29599716, 2018). "We furthermore demonstrated that the thalamic atrophy pattern in C9orf72 mutation carriers goes beyond hubs of the SN and is in good agreement with the cortical atrophy pattern detected in C9orf72 mutation carriers, indicating a retrograde degeneration of functionally connected regions." (PMID 29599716, 2018). "Shared genes with positive weights in C9orf72-bvFTD also displayed positive weights in GRN-bvFTD, indicating their common expression in regions more spared from cortical atrophy." (PMID 39920674, 2025).
dentatorubral-pallidoluysian atrophy (5 papers, 2017 to 2025). Dentatorubral pallidoluysian atrophy (DRPLA) is a rare subtype of type I autosomal dominant cerebellar ataxia (ADCA type I). "Huntington’s disease phenocopies with myoclonus and sometimes dementia can be caused by C9orf72 hexanucleotide repeat expansions, dentatorubral-pallidoluysian atrophy (DRPLA) or mitochondrial disease." (PMID 28805718, 2017).
Hallucinations (5 papers, 2019 to 2024). Perceptions in a conscious and awake state that, in the absence of external stimuli, have qualities of real perception. "Psychotic symptoms, including delusions and/or hallucinations, are relatively more common in C9orf72 positive cases of FTD-ALS than in C9orf72 negative cases." (PMID 37548032, 2024).
Primary lateral sclerosis (5 papers, 2015 to 2025). "We assembled a collection of unprecedented size of fibroblasts from patients with sporadic ALS (sALS, n = 171), primary lateral sclerosis (PLS, n = 34), ALS/PLS with C9orf72 mutations (n = 13), and healthy controls (n = 91)." (PMID 29065921, 2017).
autism spectrum disorder (4 papers, 2019 to 2023). A spectrum of developmental disorders that includes autism, and Asperger syndrome. "C4 and C5 chemical chaperones are derivatives of 4-PBA and were shown previously to inhibit protein aggregation both in vitro and in vivo in models of autism spectrum disorder (ASD) and C9orf72-related ALS." (PMID 36012668, 2022).
depression (4 papers, 2019 to 2025). "Both C9orf72+ and GRN+ demonstrated a higher rate of increase in the BDI, which is in accordance with the early predominance of depression in symptomatic mutation carriers." (PMID 40534487, 2025). "Both GRN+ and C9orf72+ showed progression of depression ratings obtained with the BDI." (PMID 40534487, 2025). "Notable nodes that appeared over at least two models included C9orf72, TREM2, APP and MAPT with relationships to input nodes of musculoskeletal and joint disorders, deafness and depression." (PMID 38383858, 2024).
epilepsy (4 papers, 2020 to 2022). A brain disorder characterized by episodes of abnormally increased neuronal discharge resulting in transient episodes of sensory or motor neurological dysfunction, or psychic dysfunction. "In contrast, in our PR-Nes line, poly-PR inclusions are enriched in the hippocampus, a common focal point of epilepsy and the area where poly-PR aggregates have been reported to be most abundant in human C9orf72 FTD." (PMID 32562018, 2020). "Our results find support in epidemiological data reporting an absence of comorbidity between ALS and epilepsy, although case reports of co-occurrence in C9orf72 repeat expansion carriers exist." (PMID 32409253, 2020).
glioblastoma (4 papers, 2019 to 2022). The most malignant astrocytic tumor (WHO grade IV). "Knock-down of c9orf72 activates the NF-κB pathway in particular in a U87 glioblastoma cell model, revealing the possibility that NF-κB takes part in c9orf72-dependent immune responses." (PMID 33918092, 2021). "siRNA-mediated knockdown of both C9orf72 isoforms in U87 glioblastoma cells or normal human astrocytes has been shown to lead to the accumulation of p62 inclusions, supporting the idea that loss of C9orf72 may lead to their formation." (PMID 31156371, 2019). "C9ORF72 is observed in a variety of human cell lines including U2OS (osteosarcoma), HeLa (cervical cancer), RKO (colon carcinoma), U87 and U251 (glioblastomas), motor neuron precursor cells (NPCs) and motor neurons (MNs) derived from human-induced pluripotent stem cells." (PMID 31612854, 2019).
lateral sclerosis (4 papers, 2020 to 2024). Primary lateral sclerosis (PLS) is an idiopathic non-familial motor neuron disease characterized by slowly progressive upper motor neuron dysfunction leading to spasticity, mild weakness in voluntary muscle movement, hyperreflexia, and loss of motor speech production. "(This would be analogous to the mutually increased stability in complex shown by amyotrophic lateral sclerosis-related proteins SMCR8 and C9ORF72, as previously reported by ourselves and others)." (PMID 37405998, 2023).
prion disease (4 papers, 2020 to 2022). A transmissible disease that is caused by a protein that is able to induce abnormal folding of normal cellular proteins, leading to characteristic spongiform brain changes, which are associated with neuronal loss without an inflammatory response. "Lysosome activity changes have been described in ALS and linked to the C9orf72 gene repeat expansions, while synthesis of phosphatidic acid and related phospholipids, including phosphatidylcholine and phosphatidylethanolamine, have been linked to ALS and prion disease pathogenesis." (PMID 34396108, 2021).
Anxiety (3 papers, 2022 to 2025). Intense feelings of nervousness, tension, or panic often arise in response to interpersonal stresses. "Unlike the gain-of-toxicity mechanism causing typical ALS-like motor deficits in mouse models 57-59, the C9orf72-null rats generated in this study did not develop motor deficits or anxiety-like behavior, similar to a C9orf72-KO mouse model." (PMID 36438488, 2022). "In addition, the elevated plus-maze test revealed no signs of anxiety in C9orf72-null rats compared with WT rats." (PMID 36438488, 2022).
autism (3 papers, 2021 to 2022). Persistent deficits in social interaction and communication and interaction as well as a markedly restricted repertoire of activity and interest as well as repetitive patterns of behavior. "In contrast, no significant alterations in ADAR1 or ADAR2 expression levels were detected in autism and C9orf72 ALS." (PMID 35327657, 2022). "None of the ALS gene carriers was diagnosed with autism or showed any clinical sign of autism; however, according to previous data, developmental tardiness might be a general trait in C9orf72 carriers." (PMID 33709219, 2021).
bipolar disorder (3 papers, 2015 to 2025). A disorder of the brain that causes unusual shifts in mood, energy, activity levels and the ability to carry out day-to-day tasks. "Similarly, only 1 individual with bipolar disorder has been found with a C9orf72 repeat expansion, although the affected parent who passed on the repeat and was originally diagnosed with bipolar disorder went on to also develop FTD." (PMID 25731823, 2015).